NLRP3 (NLR family pyrin domain containing 3)
Diseases named in the same sentence as NLRP3 in open-access papers (continued):
Sharing a sentence is not in itself a finding about the gene and the disease.
cryopyrin-associated periodic syndrome (continued). "The discovery of the NLRP3 inflammasome resulted from the uncovering of the gain of function mutation associated with cryopyrin-associated periodic syndrome (CAPS)." (PMID 38932991, 2024). "The cryopyrin-associated periodic syndromes (CAPS) represent the prototypic IL-1-mediated disease, and the IL-1β overproduction is a consequence of gain-of-function NLRP3 variants that ultimately provoke a hyperactivation of the Nlrp3-inflammasome." (PMID 38646532, 2024). "The best described inflammasomopathies result from autosomal dominant gain-of-function mutations in Nlrp3, which drive autoinflammatory diseases known as cryopyrin-associated periodic syndrome (CAPS)." (PMID 37443800, 2023). "NLRP3 mutation have been associated with cryopyrin-associated periodic syndrome (CAPS), a group of autoinflammatory disorders characterized by recurrent fevers and systemic inflammation." (PMID 37545507, 2023). "For example, cryopyrin-associated periodic syndrome (CAPS) results from dysregulated NLRP3 activity due to gain-of-function mutations in NLRP3, which leads to abnormal activation of the NLRP3 inflammasome." (PMID 37564649, 2023). "Cryopyrin-associated periodic syndromes (CAPS) have been considered autoinflammatory diseases resulting from NLRP3 gene mutations." (PMID 37854599, 2023). "The role of the NLRP3 inflammasome was first defined by the discovery of a gain of function mutation in NLRP3, leading to cryopyrin-associated periodic syndrome (CAPS)." (PMID 37598797, 2023). "It had attracted early attention since it was demonstrated that an autosomal gain-of-function mutation in the NLRP3 gene was linked to an inherited autoinflammatory disease called cryopyrin-associated periodic syndrome (CAPS)." (PMID 37006312, 2023). "Cryopyrin-associated periodic syndrome (CAPS) is a group of rare genetic autoinflammatory diseases caused by mutations in the NLRP3 gene." (PMID 37370025, 2023). "SAIDs related to the NLRP3 inflammasome include cryopyrin-associated periodic syndrome (CAPS), gout and Crohn’s disease." (PMID 37250902, 2023). "The NLRP3 gene encodes Cryopyrin, and mutations cause gain-of-function, leading to Cryopyrin-associated Periodic Syndrome (CAPS), aka NLRP3-associated autoinflammatory disease (NLRP3-AID)." (PMID 38343435, 2023). "In addition, specific phosphorylation at Ser295 blocks NLRP3’s ATPase activity, and several mutations in the vicinity of this phosphorylation site is found in Cryopyrin-associated periodic syndromes (CAPS), which are associated with spontaneous NLRP3-dependent inflammation." (PMID 38077364, 2023). "Mutations in the gene encoding NLRP3 cause a spectrum of autoinflammatory diseases known as cryopyrin-associated periodic syndromes (CAPS)." (PMID 36195671, 2023). "Gain of function variants in the NLRP3 gene resulting in aberrant NLRP3 inflammasome activation cause a family of diseases referred to cryopyrin-associated periodic syndromes (CAPS), which are marked by reoccurring systemic inflammation." (PMID 37081890, 2023). "Cryopyrin-associated periodic syndromes (CAPS) are caused by gain-of-function mutations of NLRP3, and blocking NLRP3 phosphorylation by S194A mutation abolishes LPS-induced CAPS-associated inflammasome activation." (PMID 37047097, 2023). "Cryopyrin-associated periodic syndromes (CAPS) are a group of autoinflammatory disorders caused by a gain-of-function mutation in the NLRP3 (CIAS1) gene located on the long arm of chromosome 1." (PMID 35281325, 2022). "Cryopyrin-associated periodic syndromes (CAPS) result from gain-of-function mutations in the NLRP3 gene, and mouse models of CAPS exhibit excessive activation of GSDMD, which significantly contributes to the disease etiology." (PMID 35844522, 2022). "Recent studies revealed that variants of the NLRP3 gene cause genetic diseases, including cryopyrin-associated periodic syndrome (CAPS) and non-syndromic sensorineural hearing loss (DFNA34, deafness autosomal dominant 34)." (PMID 35572943, 2022).
cryopyrin-associated periodic syndrome (continued). "MCC950 treatment effectively attenuated the inflammatory symptoms of NLRP3-related diseases, including experimental autoimmune meningitis and cryopyrin-associated periodic syndrome (CAPS)." (PMID 36387275, 2022). "MVK mutation-induced hyperimmunoglobulin D syndrome (HIDS) and NLRP3 mutation-induced cryopyrin-associated periodic syndrome (CAPS) have been added to the spectrum of SAIDs." (PMID 35123508, 2022). "Such regulatory role was lost upon mutations of NLRP3 associated with cryopyrin-associated periodic syndromes (CAPS)." (PMID 36426349, 2022). "OI was also used in peripheral blood mononuclear cells (PBMCs) isolated from patients with cryopyrin-associated periodic syndrome (CAPS), a class of diseases characterized by mutations in NLRP3 leading to spontaneous inflammasome activation." (PMID 35040439, 2022). "Gain-of-function mutations in NLRP3 are responsible for several autoinflammatory diseases, collectively termed cryopyrin-associated periodic syndromes (CAPS)." (PMID 35734577, 2022). "Cryopyrin-associated periodic syndrome (CAPS) represents a group of heterogeneous autoinflammatory disorders caused by gain-of-function (GOF) mutations in NLRP3." (PMID 35406754, 2022). "A study in Switzerland found an increase in the expected carrier rate of NLRP3 inflammasome gene mutations, which are responsible for the majority of cases of cryopyrin-associated periodic syndrome (CAPS) in PFAPA patients compared to the general population." (PMID 35310141, 2021). "The cryopyrin-associated periodic syndromes (CAPS) are usually caused by heterozygous NLRP3 gene variants, resulting in excessive inflammasome activation with subsequent overproduction of interleukin (IL)-1β." (PMID 33401496, 2021). "Cryopyrin-associated periodic syndrome (CAPS) is a prototypical autosomal dominant autoinflammatory disorder caused by gain-of-function mutations in the NLRP3 gene." (PMID 34193319, 2021). "The NLRP3 inflammasome plays an important role in the pathogenesis of the Cryopyrin-Associated Periodic Syndrome (CAPS) activating caspase-1." (PMID 33562758, 2021). "Gain-of-function mutations within NLRP3 are associated with the autoinflammatory disease cryopyrin-associated periodic syndrome (CAPS), and aberrant or excessive activation of NLRP3 has been linked to pathogenesis in SLE and various forms of arthritis." (PMID 33995417, 2021). "It is known, from human medicine, that NLRP3 mutations are associated with a group of rare hereditary autoinflammatory diseases called cryopyrin-associated periodic syndromes (CAPS)." (PMID 33808510, 2021). "Gain-of-function mutations of NLRP3 result in abnormal activation of the NLRP3 inflammasome and cause the autosomal dominant systemic autoinflammatory disease spectrum, termed cryopyrin-associated periodic syndromes (CAPS)." (PMID 34434197, 2021). "Cryopyrin-associated Periodic Syndrome (CAPS) is a rare, genetic autoinflammatory condition associated with NLRP3 gene mutations, causing upregulated innate immunity." (PMID 34013066, 2021). "Specific mutations in the NLRP3 gene have been associated with the development of a specific type of autoinflammatory manifestation termed cryopyrin-associated periodic syndromes (CAPS)." (PMID 33803783, 2021). "Eight patients (24%) were clinically diagnosed as Cryopyrin-associated periodic syndromes (CAPS) with low-penetrance NLRP3 variants (V198M, Q703K) showing overlap characteristics for the mild to moderate CAPS phenotype." (PMID 34521435, 2021). "NLRP3 gain-of-function mutation results in excessive release of IL-1β, giving rise to cryopyrin-associated periodic syndrome (CAPS), a group of rare hereditary autoinflammatory diseases." (PMID 32019187, 2020). "Gain-of-function mutations of NLRP3 cause a spectrum of autosomal-dominant systemic autoinflammatory diseases called cryopyrin-associated periodic syndromes (CAPS)." (PMID 32194497, 2020).
cryopyrin-associated periodic syndrome (continued). "The prevalence of organ-specific phenotypes (e.g., cutaneous phenotypes in NLRP1-associated syndromes) or cytokine-driven diseases (IL-18 in NLRC4-associated syndromes compared to IL-1 in NLRP3/Cryopyrin-Associated periodic Syndromes) may be largely due to differential transcriptional regulations." (PMID 33138274, 2020). "Similarly, somatic mutations in the NLRP3 gene may account for a large majority of patients (up to 70%) affected by cryopyrinopathies, a group of AD diseases caused by germline mutations in the NLRP3 gene." (PMID 33198123, 2020). "A prototypical NLRP3-linked condition is cryopyrin-associated periodic syndrome (CAPS), an inherited autosomal dominant autoinflammatory disorder characterized by recurrent episodes of inflammation and fever." (PMID 32973552, 2020). "NOMID is the most severe form of cryopyrin-associated periodic syndrome (CAPS), an autoinflammatory disease caused by heterozygous mutations in the NLRP3 gene." (PMID 32810141, 2020). "The potential contribution of the NLRP3 inflammasome to disease pathogenesis was first investigated after a gain-of-function mutation in the NLRP3 coding gene was described as a possible cause of the inflammatory condition cryopyrin-associated periodic syndrome." (PMID 32252777, 2020). "This drug was tested in light of its efficacy in patients with cryopyrin-associated periodic syndrome (CAPS) and the clinical similarities between SchS and CAPS, a monogenic autoinflammatory disease due to pathogenic variants in the NLRP3 gene." (PMID 33324407, 2020). "NLRP3 mutations cause a hereditary autoinflammatory syndrome called cryopyrin-associated periodic syndrome (CAPS), which is characterized by periodic fever, arthralgia, and rash." (PMID 32782316, 2020). "Single nucleotide mutation of the CIAS1 gene results in NLRP3 mutation, which induces constituted inflammasome activation causing cryopyrin-associated periodic syndrome (CAPS)." (PMID 31182982, 2019). "Activating mutations in NLRP3 cause cryopyrin-associated periodic syndromes (CAPS), which is characterized by systemic inflammation with fever and blood neutrophilia." (PMID 31170158, 2019). "Cryopyrin-associated periodic syndrome (CAPS) is a rare autoinflammatory disease, caused by gain of function mutation in NLRP3 resulting in excess production of interleukin-1 (IL-1)." (PMID 31287007, 2019). "Cryopyrin-associated periodic syndromes (CAPS) are a group of rare, monogenic, autoinflammatory diseases caused by a gain of function mutation in NLR family pyrin domain containing 3 (NLRP3), which results in excess production of interleukin-1 beta (IL-1β)." (PMID 31287007, 2019). "Cryopyrin-associated periodic syndromes (CAPS) are caused by a mutation in NLRP3 inflammasome, resulting in increased IL-1β and IL-18 production, but impaired production of the anti-inflammatory IL-6 and IL-1RA cytokines." (PMID 29515591, 2018). "Mutated NLRP3 assembles a hyperactive inflammasome, which causes excessive secretion of interleukin (IL)-1β and IL-18 and, ultimately, a spectrum of autoinflammatory disorders known as cryopyrinopathies of which neonatal-onset multisystem inflammatory disease (NOMID) is the most severe phenotype." (PMID 30388107, 2018). "Cryopyrin-associated periodic syndrome (CAPS) is auto inflammatory disorder and associated with Nlrp3 mutations." (PMID 28148962, 2017). "The dysregulated production of IL-1β by the NLRP3 inflammasome is the main reason for the development of Cryopyrin-Associated Periodic Syndromes (CAPS) which is caused by a mutation in NLRP3 gene." (PMID 27672241, 2016). "Gain-of-function NLRP3 mutations cause a subset of autoinflammatory diseases collectively called cryopyrin-associated periodic syndrome (CAPS)." (PMID 25761061, 2015). "This study aimed to clarify the interaction between CARD8 and wild-type NLRP3 as well as mutant forms of NLRP3 linked with cryopyrin-associated periodic syndromes (CAPS)." (PMID 24517500, 2014).
cryopyrin-associated periodic syndrome (continued). "Mutations in NLRP3 have been described in the cryopyrin-associated periodic syndromes (CAPS; cryopyrin is a name previously used for NLRP3), whereas specific NLRP-3 polymorphisms have been associated with Crohn's disease." (PMID 20195505, 2010). "Cryopyrin-associated periodic syndrome (CAPS), an autosomal dominant disease, is caused by NLRP3, and Blau syndrome, an autosomal dominant disease, is caused by NOD2 mutations." (PMID 40282361, 2025). "We next tested whether palmitoylation and phase separation was important for the Cryopyrin-associated periodic syndrome (CAPS)-associated NLRP3 variants." (PMID 40164768, 2025). "Gain-of-function mutations in NLRP3 lead to constitutive inflammasome activation and excessive IL-1β production and are associated with the development of cryopyrin-associated periodic syndrome (CAPS)." (PMID 41087719, 2025). "Blocking S194 phosphorylation suppresses NLRP3 inflammasome activation in cryopyrin-associated periodic syndrome (CAPS) patients, suggesting its importance as a therapeutic target for treating NLRP3-related diseases." (PMID 40307577, 2025). "Inflammasomes take their name from the sensor component; of these, the NLRP3 inflammasome is the most studied: the discovery that gain-of-function NLRP3 mutations caused the cryopyrin-associated periodic syndrome (CAPS) was a breakthrough at the doorway of the post-genomic medicine era." (PMID 40076498, 2025). "Notably, NLRP3 gain-of-function mutations cause autoinflammatory cryopyrin-associated periodic syndrome (CAPS)." (PMID 39218978, 2024). "Gain-of-function mutations in NLRP3 are linked to cryopyrin-associated periodic syndromes (CAPS)." (PMID 38416826, 2024). "In 2022, the inhibitor passed a phase 1 clinical trial followed by an ongoing phase 2 study for safety and clinical activity in patients with cryopyrin-associated periodic syndrome (CAPS), a condition caused by an NLRP3 gene mutation (NCT05812781)." (PMID 38945951, 2024). "Also, cryopyrin-associated periodic syndrome (CAPS) patients, owing to a genetic condition, have constitutively high NLRP3 and ASC inflammasome activation and are at high risk of developing AA amyloidosis." (PMID 39080493, 2024). "Due to the NLRP3 mutation, this pattern is comparable to that seen in Cryopyrin-Associated Periodic Syndromes (CAPS), which suggests that patients with FMF may have distinct autoinflammatory pathways." (PMID 39335710, 2024). "NLRP3-AID, formerly termed cryopyrin-associated periodic syndrome (CAPS), comprises a group of disorders arising from monoallelic, gain-of-function mutations in the NLRP3 (CIAS1) gene, which induce neutrophil-mediated inflammation." (PMID 37329408, 2023). "Cryopyrin-associated periodic syndromes (CAPS) are autoinflammatory disorders mediated by dysfunctional inflammasome activation caused by heterozygous germline or somatic gain-of-function mutations in the NLRP3 gene." (PMID 35567665, 2022). "Notably, mutations of genes encoding for the components of the proteins involved in the inflammasome (NLRP3) are implicated in the AIF called Cryopyrin-associated periodic syndromes (CAPS)." (PMID 35464438, 2022). "These agents have been proven to be effective in the treatment of Cryopyrin-associated periodic syndromes (CAPS) caused by NLRP3 gene mutations and have also been applied in clinical trials for other NLRP3-associated disorders." (PMID 35250572, 2022). "CAPS (cryopyrin-associated periodic syndrome) is an autoinflammatory disease characterized by recurrent systemic inflammation and caused by mutations in the NLRP3 gene." (PMID 32640751, 2020). "Certain phosphorylation events in NLRP3 also keep the molecule inactive, which were reported to be lost under chronic inflammatory conditions like CAPS (cryopyrin-associated periodic syndromes) and inflammatory bowel disease." (PMID 32230726, 2020).
cryopyrin-associated periodic syndrome (continued). "The most common monogenic SAIDs are FMF, NLRP3-associated autoinflammatory disease (NLRP3-AID; formerly known as Cryopyrin associated periodic syndromes - CAPS), and TNF receptor-associated periodic syndrome (TRAPS)." (PMID 32019685, 2020). "A potent and selective small-molecule inhibitor of NLRP3, MCC950, has been developed and shown to attenuate NLRP3-associated syndromes, including experimental autoimmune encephalomyelitis and cryopyrin-associated periodic syndrome, in mice." (PMID 30944389, 2019). "Activation of NLRP3 inflammasome has a key role in the pathogenesis of other autoinflammatory diseases, such as cryopyrinopathies." (PMID 31866997, 2019). "In addition to NLRP3 activation anomalies, there are also NLRP3 genetic abnormalities collectively termed as cryopyrin-associated periodic syndromes (CAPS)." (PMID 31749805, 2019). "Furthermore, gain-of-function mutations in the NLRP3 gene (also known as CIAS1) were associated with the disease spectrum of cryopyrin-associated periodic syndrome (CAPS) in 2001." (PMID 32082075, 2019). "Moreover, gain-of-function mutations in and around the central NAIP, CIITA, HET-E, and TP1 (NACHT) domain of NLRP3 cause three autosomal dominantly inherited periodic fever syndromes that together are known as cryopyrin-associated periodic syndrome (CAPS)." (PMID 31525186, 2019). "Mutations in the NLRP3 gene are associated with the dominantly inherited autoinflammatory diseases known as cryopyrin-associated periodic syndromes (CAPS), including familial cold autoinflammatory syndrome, Muckle–Wells syndrome, and chronic infantile neurological cutaneous and articular syndrome." (PMID 31590215, 2019). "These three diseases are collectively known as cryopyrin-associated periodic syndrome (CAPS), suggesting that the disease-associated variants of NLRP3 probably encode a hyperactive version of NLRP3 which promotes excessive production of IL-1β." (PMID 29850543, 2018). "Moreover, aberrant activation of NLRP3 caused by mutations has been implicated in the pathogenesis of Cryopyrin-associated periodic syndrome (CAPS) and other inflammatory diseases." (PMID 30349539, 2018). "The NLRP3 inflammasome gained a lot of attention due to the causality of NLRP3 mutations in cryopyrin-associated periodic syndromes (CAPS), an auto-inflammatory pathology characterized by high levels of IL-1β secretion from peripheral blood mononuclear cells (PBMCs) of patients." (PMID 28403163, 2017). "Additionally, QUC inhibited IL-1β in Cryopyrin-Associated Periodic Syndromes (CAPS) macrophages, where NLRP3 inflammasome is constitutively activated." (PMID 28148962, 2017). "Cryopyrin-associated periodic syndrome (CAPS) is caused by gain-of-function NLRP3 mutations." (PMID 29163488, 2017). "Inflammasome activation leads to efficient defense against pathogens, while missense mutations in the NLRP3 protein-encoding gene (Cias1) cause autoinflammatory disorders cryopyrinopathies (i.e. cryopyrin-associated periodic syndromes, CAPS), where IL-1β is constitutively processed." (PMID 27467658, 2016). "The effect of OME on IL-1β secretion was investigated on monocytes from patients affected by cryopyrin-associated periodic syndrome (CAPS), a very rare autoinflammatory disease where gain-of-function mutations in the inflammasome gene NLRP3 cause huge secretion of IL-1β." (PMID 27441656, 2016). "Mutations in the cold-induced autoinflammatory syndrome 1 (CIAS1) gene encoding NLRP3 result in cryopyrin-associated periodic syndromes (CAPS) characterized by recurrent episodes of systemic inflammatory attacks in the absence of infection or autoimmune diseases." (PMID 24517500, 2014). "SchS shares many features with the hereditary autoinflammatory syndrome cryopyrin-associated periodic syndrome (CAPS), which is caused by NLRP3 mutations that lead to enhanced IL-1β production that induces chronic systemic inflammation, including fever and joint pain." (PMID 25905009, 2014).